VHL (von Hippel-Lindau tumor suppressor)
Diseases named in the same sentence as VHL in open-access papers (continued):
Sharing a sentence is not in itself a finding about the gene and the disease.
pheochromocytoma (continued). "The risk for the various manifestations of VHL was found to be associated with the genotype, with patients harboring a non-missense pathogenic variants leading to a truncated VHL protein having a very low risk of developing pheochromocytoma." (PMID 36980625, 2023). "In parallel, mutations in VHL also induce the occurrence of other tumors, including cerebellar and spinal hemangioblastomas, retinal angiomas, endolymphatic sac tumors, pancreatic neuroendocrine tumors, and pheochromocytoma." (PMID 35562974, 2022). "Both the Y98H and Y112H VHL mutations are classically associated with VHL Type 2a disease with a high penetrance of pheochromocytoma, but while the Y112H mutation appears to result in hemangioma/hemangioblastoma in only 20% of cases, the Y98H mutation displays a greater penetrance at ~50%." (PMID 36040300, 2022). "Type 1 VHL mutations are at a lower risk of pheochromocytoma and tend to have truncating mutations to VHL, while types 2A, 2B and 2C arise from missense mutations and have a higher risk of pheochromocytoma." (PMID 36421797, 2022). "Characteristics and mutation sites of four patients with VHL-mutated pheochromocytomas." (PMID 33828526, 2021). "For example, tumors belonging to Cluster 1 (pseudohypoxia) may present as either pheochromocytoma or paraganglioma, often occur at a younger age (especially those with germline VHL mutation) and frequently manifest as multiple and/or recurrent." (PMID 34572828, 2021). "A greater number of studies have been dedicated to VHL-associated pheochromocytomas." (PMID 34025587, 2021). "A pseudohypoxic transcriptional signature characterizes pheochromocytomas and paragangliomas (PPGLs) of the cluster I, mainly represented by tumors with mutations in von Hippel–Lindau (VHL), endothelial PAS domain-containing protein 1 (EPAS1), or succinate dehydrogenase (SDH) subunit genes." (PMID 31142060, 2019). "Thirteen patients were found with the c.334T > A p.Tyr112Asn mutation, seven of whom had RCC, and one of these patients had a pheochromocytoma, which suggests that this type of mutation causes the VHL type 1 phenotype, as most of the patients presented with RCC." (PMID 31620170, 2019). "Germline VHL, SDHx and FH mutations may predispose to phaeochromocytoma/paraganglioma and RCC, and on rare occasions renal tumours have been reported in association with mutations in the phaeochromocytoma genes TMEM127 and MAX." (PMID 29680948, 2018). "Furthermore, mutations in the VHL gene have been found in both sporadic and hereditary head and neck paragangliomas/pheochromocytomas." (PMID 28187001, 2017). "Moreover, some genetic investigations showed a mutation in the VHL ex.1 p.Y112 C gene responsible for the hereditary form of phaeochromocytoma which confirmed von Hippel-Lindau syndrome." (PMID 26268347, 2015). "Interestingly, it has been noted that the bi-allelic loss of VHL seems to be incompatible with pheochromocytoma development and that most cases of type 2 VHL disease (high risk of pheochromocytomas) are caused by missense mutations of the VHL gene." (PMID 25385837, 2014). "Mutations of the von Hippel–Lindau (VHL) gene are associated with pheochromocytomas and paragangliomas, but the role of VHL in sympathoadrenal homeostasis is unknown." (PMID 25385837, 2014). "VHL Type 2 families have a high risk of developing pheochromocytoma." (PMID 20560986, 2011). "Suppressed SDHB protein can be found in pheochromocytomas with loss of VHL." (PMID 20398431, 2010). "Mutations in the VHL gene cause von Hippel-Lindau disease, a dominantly inherited familial cancer syndrome predisposing to a variety of malignant and benign neoplasms, including clear cell renal carcinoma and pheochromocytoma." (PMID 20398431, 2010).
pheochromocytoma (continued). "In sporadic pheochromocytomas, somatic mutations of VHL or RET are found in less than 10% of tumors, suggesting a possible role in tumorigenesis, whereas the prevalence and role of such mutations in hereditary pheochromocytomas such as those occurring in MEN 2 is not known." (PMID 16707008, 2006). "In all of these MEN 2A-associated pheochromocytomas as well as in the present study of thyroid C cell specimens, regular wild-type VHL alleles were detected in normal control tissue confirming the presence of two wild-type alleles and excluding the presence of VHL disease." (PMID 16707008, 2006). "Also, clinical similarities besides pheochromocytoma have been noted in families with germline mutations of VHL and SDHB." (PMID 16103922, 2005). "It remains to be tested whether the predominant hypoxic-angiogenic profile of pheochromocytomas with VHL and SDH mutations will render these tumors targets for antiangiogenic therapies." (PMID 16103922, 2005). "Importantly, suppressed SDHB levels were also found in the majority of tumors with VHL mutations and sporadic pheochromocytomas from Cluster 1 tested by immunoblots." (PMID 16103922, 2005). "However, mutations associated with type 2C (predisposition to pheochromocytoma only) VHL disease complement defective HIF regulation but bind fibronectin with lower affinity than wild-type VHL." (PMID 15361934, 2004). "Similarly, germline mutations in the VHL TSG are an important cause of phaeochromocytoma susceptibility, but somatic VHL mutations are rare in phaeochromocytoma." (PMID 15505628, 2004). "Similarly, the Type 2c VHL mutant G93S was linked with pheochromocytoma across multiple generations in a family with VHL disease, but further diagnostic workup revealed two retinal angiomas in the index patient and bilateral renal cysts in the index patient’s father." (PMID 36040300, 2022). "More than 95% of patients with VHL disease will have a detectable VHL gene mutation and well-defined genotype–phenotype mean that the nature of the mutation may predict likely tumour risks (e.g. risk of phaeochromocytoma is small with truncating mutations and exonic deletions)." (PMID 29680948, 2018). "For instance, VHL disease and SDH-related syndromes both predispose patients to multiple NETs through shared HIF pathways, with VHL patients developing pheochromocytomas and pancreatic NETs." (PMID 41323164, 2026). "The frequency of pheochromocytoma is 10–20% in VHL, 50% in MEN2, and 3% in NF1, with bilateral adrenal pheochromocytomas being the most common." (PMID 40649858, 2025). "These mutations are linked to hereditary syndromes like VHL, NF1, and MEN2 and can lead to tumors in multiple tissues, including pheochromocytomas and paragangliomas." (PMID 40649858, 2025). "Overexpression of COX4I2 is notable in tumors harboring VHL or SDH loss-of-function mutations, highlighting its potential as a biomarker of pheochromocytoma." (PMID 40649858, 2025). "Four general VHL phenotypes (type 1, type 2A, type 2B, and type 2C) have been proposed based on the likelihood of developing pheochromocytoma." (PMID 40427061, 2025). "Among them, three patients had large fragment deletions of the VHL gene, and all the three patients suffered from unilateral pheochromocytoma." (PMID 41179499, 2025). "These new genetic markers, along with the susceptibility genes like RET, NF1, VHL, SDH, and fumarate hydratase, are expanding our understanding of the genetic basis of pheochromocytoma." (PMID 40649858, 2025). "Further, the prevalence of vHL-associated conditions aside from RCC and pheochromocytoma was dramatically less than the prevalence reported in the literature." (PMID 39678829, 2024). "In our study, genetic counseling was provided to patients with hereditary pheochromocytomas, and the genetic results confirmed the presence of vHL, NF‐1, and MEN2A." (PMID 38747189, 2024).
pheochromocytoma (continued). "CNS hemangioblastoma was observed to coexist in 80.65% of our pedigrees with VHL-associated RH and in a higher percentage compared to RCC (22.58%), pancreatic cysts (16.13%) and pheochromocytoma (6.45%)." (PMID 39336783, 2024). "The susceptibility to pheochromocytoma can be linked to germline pathogenic variants in the RET proto-oncogene and tumor suppressor genes such as von Hippel-Lindau (VHL), and Neurofibromatosis type 1 (NF1)." (PMID 39735644, 2024). "VHL and SDH complex share a hallmark feature of Pheochromocytoma, but there are some differences between them." (PMID 36936415, 2023). "According to the guidelines of the American College of Medical Genetics and Genomics, this variant is pathogenic and co-segregated with a total population frequency of 0, and was found associated with pheochromocytoma (OMIM:171300) and VHL (OMIM:193300)." (PMID 36595857, 2022). "At this time, genetic screening was performed considering his family history of pheochromocytoma, and he was diagnosed with VHL." (PMID 35951216, 2022). "Type 2c VHL disease has perplexed the field as Type 2c pVHL mutants appear to regulate HIFα in a manner similar to wild-type pVHL, which would suggest that pheochromocytoma is uncoupled from HIFα degradation." (PMID 36040300, 2022). "Genetic screening was performed considering his family history of pheochromocytoma, and he was diagnosed with VHL." (PMID 35951216, 2022). "In a previous study of 31 VHL patients, PNET and pheochromocytomas were significantly associated with missense variants whereas pancreatic cysts were more frequent in patients with nonmissense variants." (PMID 35475554, 2022). "Another finding has been the overexpression of miR-885-5p in MEN2-related pheochromocytoma compared with VHL- NF1-, sporadic recurring, and sporadic benign pheochromocytomas." (PMID 33810219, 2021). "In pheochromocytoma, the most common mutations occur in genes involved in the VHL/HIF axis, including PHD, VHL, and HIF." (PMID 34239688, 2021). "The aim of this review is to summarize current knowledge on endocrine glands tumors associated with VHL, NF1, TSC, and CS, especially neuroendocrine tumors and pheochromocytomas/paragangliomas." (PMID 34025587, 2021). "Genotype-phenotype correlations are characteristic of VHL mutations in VHL syndrome, which is classified into type 1 (without pheochromocytoma but with high risk for clear cell RCC) and type 2 (with pheochromocytoma)." (PMID 32612654, 2020). "Mutations in VHL, RET, NF1, SDHB, and SDHD account for 90% of all pheochromocytomas and paragangliomas." (PMID 32266384, 2020). "Phosphorylation sites found to be frequently mutated in both renal manifestations of VHL (collectively including RCC, ccRCC, renal cysts) and pheochromocytoma (right)." (PMID 30943211, 2019). "Both germline and somatic mutations in KIF1B gene have been found in pheochromocytoma, occasionally occurring in combinations with mutations in other genes, such as NF1, RET, VHL, and SDHx." (PMID 29504908, 2018). "In face of the malignant presentation, molecular studies were conducted to screen mutations in five genes related to pheochromocytoma: SDHB, SDHD, SDHC, MAX and VHL." (PMID 29768630, 2018). "Conversely, both germline and somatic mutations in this gene have been found in pheochromocytomas, occasionally occurring in combinations with mutations in other genes, such as NF1 or RET as well as VHL or SDHx." (PMID 28187001, 2017). "Specific genotype–phenotype correlations in affected families led to the classification of VHL subtypes into types 1 and 2, primarily based on the presence of pheochromocytoma." (PMID 28785532, 2017). "Pheochromocytomas usually present in the second decade of life in VHL patients and rarely transform into malignant tumors." (PMID 28785532, 2017). "VHL Type 1 families are characterized by HB with RCC and are thought to have a low risk of pheochromocytoma." (PMID 27069690, 2016).
pheochromocytoma (continued). "Considering the occurrence of phenotypic heterogeneity and interfamilial variations in VHL, historically it has been classified into five disease phenotypes based on the probability of consistent occurrence of either pheochromocytoma or RCC in the kindred." (PMID 27069690, 2016). "The COMETE cohort has demonstrated the occurrence of somatic mutations in VHL and RET genes in 14% of sporadic pheochromocytoma/paraganglioma, one germ-line, and three somatic mutations in the MAX were described by the same cohort." (PMID 26347711, 2015). "Besides pheochromocytomas, carotid body (CB) paragangliomas and other tumors of neural crest lineage are frequently associated with VHL disease, a hereditary syndrome caused by mutations in the VHL gene and characterized by the occurrence of tumors in multiple tissues." (PMID 25385837, 2014). "It was later observed that the VHL gene is also inactivated in sporadic renal cell carcinoma, hemangioblastoma and pheochromocytoma." (PMID 23843833, 2012). "HIF leads to an increase in the production of tyrosine hydroxylase, and subsequently, overproduction of catecholamine in VHL-related pheochromocytoma." (PMID 23843833, 2012). "Analysis of von Hippel Lindau (VHL) coding exons and flanking intronic sequences in DNA from a proband with pheochromocytoma and islet cell tumor was performed." (PMID 20560986, 2011). "Less then 12 % of VHL patients express both neuroendocrine tumors of the pancreas and pheochromocytomas." (PMID 20560986, 2011). "The cluster containing VHL and SDH associated phaeochromocytomas was characterized by a transcription signature of reduced oxidoreductase activity and increased angiogenesis and hypoxia." (PMID 19432956, 2009). "In patients with familial pheochromocytoma screening for gene mutations in the RET, VHL, SDHB and SDHD gene is recommended since different familial syndromes can be revealed." (PMID 17922902, 2007). "This family appeared to have only pheochromocytomas as part of the VHL syndrome and has therefore been classified as VHL type 2C." (PMID 17922902, 2007). "In a recent study, we detected inactivating somatic mutations of VHL and LOH at 3p25/26 in several MEN 2A-related pheochromocytomas." (PMID 16707008, 2006). "Of note, pheochromocytoma was the sole manifestation in one of the VHL families in this series (tumors 155 and 156)." (PMID 16103922, 2005). "Whether pregnancy affects the progression of VHL lesions, particularly hemangioblastomas and pheochromocytomas, remains controversial." (PMID 41409938, 2025). "Type 2 VHL is usually associated with missense mutations encoding a protein with limited activity and includes pheochromocytoma with or without other clinical findings." (PMID 40620865, 2025). "In addition to the classic syndromes, MEN 2, VHL, and NF1, germline succinate dehydrogenase gene mutations (SDHx) are included as part of the pheochromocytoma syndromes." (PMID 40709162, 2025). "HIF-2α is preferentially upregulated in VHL-mutant pheochromocytomas and paragangliomas." (PMID 40620865, 2025). "The overall survival rate for VHL patients with pheochromocytoma was reported to be more than 90%." (PMID 38344311, 2024). "Furthermore, the role of genetic testing in the management of pheochromocytoma in VHL patients is an area of ongoing research." (PMID 38344311, 2024). "Type 2c VHL disease is associated with pheochromocytoma without other disease phenotypes, and several Type 2c pVHL mutants were found to promote HIFα polyubiquitylation at seemingly wild-type levels." (PMID 36040300, 2022). "For example, a patient with bilateral pheochromocytoma and no other VHL-related symptoms was found to harbor a Y175C VHL mutation." (PMID 36040300, 2022). "In addition, in cases of VHL-associated SCN, we should be careful about the onset of other neoplastic diseases, such as hemangioblastoma of central nervous system, RCC and pheochromocytoma." (PMID 34191152, 2021).
pheochromocytoma (continued). "miR-541 has been shown to be upregulated in VHL compared with sporadic recurring pheochromocytomas." (PMID 33810219, 2021). "Therefore, this procedure seems particularly recommended, when feasible, in VHL- and NF1-associated pheochromocytomas, and it can be performed in both adult and pediatric populations." (PMID 34025587, 2021). "VHL gene was also reported in 19.1% of the cases as the reason for bilateral pheochromocytoma." (PMID 33777662, 2021). "For example, VHL-associated pheochromocytomas are norepinephrine-secreting, whereas SDHx tumors may secrete dopamine and norepinephrine and MEN2A-related pheochromocytomas may secrete norepinephrine and epinephrine." (PMID 32751501, 2020). "Our study shows that the synonymous VHL mutation c.414A > G can within 7 years induce pediatric retinal hemangioblastoma in absence of pheochromocytoma." (PMID 32106822, 2020). "For example, data derived from microarrays and proteomics have shown reduced expression of various components of the regulated secretory pathway (e.g., SNAP25, syntaxin, rabphilin 3A, annexin) in VHL-related pheochromocytomas compared to RET-related pheochromocytomas." (PMID 31390824, 2019). "In addition, it was demonstrated that the expression of VMAT1 mRNA was significantly higher in pheochromocytomas from VHL compared to MEN2 patients." (PMID 31390824, 2019). "In addition, the rate constant for baseline catecholamine secretion was found to be 20-fold higher in VHL- than in RET-related pheochromocytoma." (PMID 31390824, 2019). "It is indicated that VHL promoter hypermethylation may play an important role in pheochromocytoma and abdominal paraganglioma development." (PMID 29933410, 2018). "In particular, these small mutations may impair the ability of the VHL protein to effect the formation of the fibronectin matrix while leaving the HIF interaction ability intact, which leads to the development of pheochromocytomas." (PMID 28187001, 2017). "Phenotypes of VHL are based on the absence (type 1) or presence (type 2) of pheochromocytoma." (PMID 28326249, 2014). "Previous reports in humans, based on gene expression profiling and unsupervised hierarchical clustering, demonstrate a tight association between pheochromocytomas with VHL and SDH mutations, which distinguishes them from pheochromocytomas with MEN2, RET, and NF1 mutations." (PMID 24465590, 2014). "In this study, it was found that 24% of the patients who presented with nonsyndromic pheochromocytoma and without family history of the disease had mutations in VHL, RET, SDHD, and SDHB genes." (PMID 24899893, 2014). "Importantly, these VHL mutants ubiquitinate and degrade HIF as efficiently as wild-type VHL, which suggests that HIF-independent function(s) of VHL play a role in the generation of pheochromocytomas." (PMID 21386990, 2011). "Although NBs and pheochromocytomas share a common origin, carcinogenesis in NBs is not linked to pathogenic VHL mutations, as in a subset of pheochromocytomas." (PMID 20398431, 2010). "A recent genome-wide expression study of phaeochromocytomas identified two distinct clusters: one containing SDH- and VHL-associated phaeochromocytomas and another containing MEN2- and NF1-associated phaeochromocytomas, while both clusters contained sporadic cases." (PMID 19432956, 2009). "VHL is a tumor suppressor gene responsible for the VHL disease, a hereditary neoplastic syndrome characterized by a predisposition to RCC, retinal and central nervous system hemangioblastomas, pancreatic cysts and pheochromocytomas." (PMID 19763184, 2009). "Germline VHL mutations are rare in simplex cases of unilateral pheochromocytoma(i.e., an affected individual with no family history of VHL syndrome), unless theindividual is younger than age 20 years." (PMID 19009041, 2008). "VHL type 2C confers an increased risk of pheochromocytomas without other manifestations of the disease." (PMID 17922902, 2007).